KLF5 (KLF transcription factor 5)
Diseases named in the same sentence as KLF5 in open-access papers (continued):
Sharing a sentence is not in itself a finding about the gene and the disease.
chronic obstructive pulmonary disease (3 papers, 2016 to 2021). A chronic and progressive lung disorder characterized by the loss of elasticity of the bronchial tree and the air sacs, destruction of the air sacs wall, thickening of the bronchial wall, and mucous accumulation in the bronchial tree. "Additionally, KLF5 was revealed to be not only upregulated in small airways and pulmonary vessels of chronic obstructive pulmonary disease patients, but was also implicated in the remodeling of chronic obstructive pulmonary disease tissues." (PMID 34118928, 2021). "KLF5 displayed upregulation in chronic obstructive pulmonary disease tissues, and downregulated KLF5 expression by miR-145-5p could exert protection against cigarette smoke extract-induced airway epithelial cell apoptosis as well as inflammation." (PMID 34118928, 2021). "In a cellular model of chronic obstructive pulmonary disease, KLF5 as a target of miR-145-5p, when suppressed by miR-145-5p upregulation, could potentially protect against cigarette smoke exposure-induced bronchial epithelial cell inflammation and inflammation-related apoptosis." (PMID 34551684, 2021).
colon adenocarcinoma (3 papers, 2019 to 2022). "Samples from healthy individuals and colon adenocarcinoma biopsies were used as controls, and both had high levels of KLF5." (PMID 35393949, 2022). "KLF5 was used as an example to analyze its coexpressed genes in colon adenocarcinoma." (PMID 34367275, 2021).
endothelial dysfunction (3 papers, 2011 to 2025). In vascular diseases, endothelial dysfunction is a systemic pathological state of the endothelium (the inner lining of blood vessels) and can be broadly defined as an imbalance between vasodilating and vasoconstricting substances produced by (or acting on) the endothelium. "Recently, KLF5 has been shown to be implicated in endothelial dysfunction." (PMID 21951574, 2011). "Oxidized low-density lipoprotein (a key factor in atherogenesis) induces KLF5 in VSMCs, which can worsen endothelial dysfunction." (PMID 41378097, 2025). "KLF5 can contribute to endothelial dysfunction by regulating the expression of genes involved in vascular tone, permeability, and inflammation." (PMID 36984888, 2023).
head and neck cancer (3 papers, 2021 to 2025). A primary or metastatic malignant neoplasm affecting the head and neck. "It is recently reported that KLF5 transcripts are actively regulated by three-dimensional structural changes through promoter–enhancer binding in head and neck cancer cells." (PMID 34707247, 2022). "Similarly, studies of cell line databases consistently showed increased KLF5 expression in gastrointestinal, bladder, lung, and head and neck cancers." (PMID 41583492, 2025).
liver disease (3 papers, 2021 to 2025). "Aberrant KLF5 expression is associated with the malignant progression of liver diseases through direct or indirect effects at the transcriptional or posttranslational level." (PMID 40697993, 2025). "Inhibition of KLF5 prevents endothelial dysfunction and overexpression of proinflammatory cytokines, thus abrogating the progression of splenomegaly in portal hypertension." (PMID 33493334, 2021). "Our results suggest that K5-Cre; Klf5fl/fl mice can be a valuable complement to existing mouse models of liver disease and further highlight the role of Klf5 for liver pathology." (PMID 34117597, 2021). "Abnormal KLF5 levels have been reported in benign and malignant liver diseases." (PMID 40697993, 2025). "Furthermore, elevated expression of KLF5 is also found in portal hypertension, accompanied by increased IL-1β, IL-6, IL-17, and TNF-α." (PMID 33493334, 2021).
osteosarcoma (3 papers, 2020 to 2025). A usually aggressive malignant bone-forming mesenchymal neoplasm, predominantly affecting adolescents and young adults. "The results showed that KLF5 expression was up‐regulated in osteosarcoma, most significantly in 143B and U2OS cells." (PMID 32285603, 2020). "Krüppel‐like factor 5 (KLF5) is a key transcriptional regulator of cellular proliferation whose overexpression is observed in osteosarcoma cell lines (U2OS, 143B, MG63 and SAOS2)." (PMID 32285603, 2020). "In osteosarcoma cell lines, ML264 treatment found to inhibits the activation of STAT3 and proteins associated with EMT by decreasing KLF5 expression." (PMID 33424607, 2020). "First, we measured KLF5 expression in hFOB1.19 cells (human osteoblast cell line) and different osteosarcoma cell lines using qRT‐PCR." (PMID 32285603, 2020). "Although KLF5 activity is implicated in many types of cancer, the effects of its inhibition have not been investigated in detail in osteosarcoma." (PMID 32285603, 2020). "In our study, ML264 reduced the expression of KLF5 at both the transcriptional and protein level, which, in turn, altered the expression of various downstream molecules to hinder proliferation and metastasis of osteosarcoma cells." (PMID 32285603, 2020). "In conclusion, ML264 inhibited the JAK2/STAT3 and Wnt/β‐catenin signalling pathways via down‐regulation of KLF5 and EGR1 expression, thereby inhibiting proliferation and metastasis of osteosarcoma cells." (PMID 32285603, 2020).
acute kidney injury (2 papers, 2023 to 2024). Sudden and sustained deterioration of the kidney function characterized by decreased glomerular filtration rate, increased serum creatinine or oliguria. "Regarding the kidney, recent studies showed that KLF2, KLF4, KLF5, KLF6, and KLF15 were distributed in glomeruli and renal tubules and played important roles in the occurrence and development of proteinuric glomerular diseases and acute kidney injury 28-32,53,54." (PMID 36632460, 2023).
acute pancreatitis (2 papers, 2023). An acute inflammatory process that leads to necrosis of the pancreatic parenchyma. "Deleting Klf5 in the context of acute pancreatitis by itself or in the context of Kras mutations blocks ADM and mPanIN building, resulting in decreased Krt19 and Ccnd1 and upregulated levels of Ndrg2, which were correlated with the reduced level of STAT3 phosphorylation." (PMID 37239940, 2023). "Analysis of tissues originated from mouse models of acute pancreatitis and specimen from pancreatitis patients shows that KLF5 is induced in pancreatic acinar cells and is crucial to ADM and the formation of early neoplasia." (PMID 37239940, 2023). "Our previous study demonstrated that Krüppel-like factor 5 (KLF5) is necessary for forming acinar-to-ductal metaplasia (ADM) in acute pancreatitis." (PMID 38001687, 2023).
adenoma (2 papers, 2010 to 2014). A neoplasm arising from the epithelium. "In addition, we recently showed that adenoma formation in ApcMin mice was significantly abrogated when ApcMin mice were bred to mice heterozygous for Klf5." (PMID 20298593, 2010). "Adenomas and carcinomas in mice that express oncogenic KRASV12 from the intestine-specific villin promoter have increased KLF5 expression." (PMID 20298593, 2010). "Elevated levels of two particular Fbxw7 substrates, Klf5 and Tgif1, were found in normal intestine and adenomas of R482Q/+, R482Q/R482Q and Fbxw7−/− mice, but not Fbxw7+/− animals." (PMID 23676439, 2014).
Atrophy (2 papers, 2022 to 2025). Any weakening or degeneration, especially through lack of use. "Further, Am80, a KLF5 inhibitor, inhibits dexamethasone- and microgravity-induced muscle atrophy in vitro, and oral Am80 improves disuse- and dexamethasone-induced muscle atrophy in mouse." (PMID 35812340, 2022). "KLF5 and KLF10 are key mediators of early muscle atrophy, whereas FOS increases after denervation‐induced muscle atrophy." (PMID 39435630, 2025).
Autoimmunity (2 papers, 2018 to 2024). The occurrence of an immune reaction against the organism's own cells or tissues. "Importantly, heterozygous deficiency of both Fli1 and KLF5 results in the development of all three features of SSc, including autoimmunity, vasculopathy, and fibrosis." (PMID 29544542, 2018). "Mice with a double heterozygous deficiency of Krüppel-like factor-5 (Klf5) and Fli1 genes represent an SSc animal model able to recapitulate all the three main pathological features of the disease in their specific chronological order, i.e., autoimmunity, microvasculopathy, and tissue fibrosis." (PMID 38927538, 2024).
cardiomyopathy (2 papers, 2024). A disease of the heart muscle or myocardium proper. "Comparison of the regulon activity between HCM and NC identified activation of transcription factors (TFs) in HCM including KLF5 which was associated with cardiomyopathy,21, 22ETV1 which is involved in atrial remodelling, and TCF4 which participates in the WNT signalling pathway." (PMID 37766635, 2024).
cervical intraepithelial neoplasia (2 papers, 2017 to 2021). "Additionally, we performed immunofluorescence staining to examine co-expression of Eppk1 and KLF5 proteins in different pathologic cervical tissues (37 normal cervical tissues, cervical intraepithelial neoplasia (CIN) tissues (CIN I: 31 cases; CIN II-III: 47 cases) and 40 CC tissues)." (PMID 33827480, 2021).
cervical tumors (2 papers, 2017 to 2025). "We initially observed KLF5 and TNFRSF11a mRNA and protein coexpression in cervical tumours, and identified KLF5 as an effector of TNFRSF11a." (PMID 29146991, 2017). "However, integrated HPV31 genomes from several cervical tumors overlap integration hotspots, including those on chromosomes 3 and 17 that contain the KLF5/KLF12 and KRT9/KRT14 genes, respectively." (PMID 40892869, 2025).
colorectal adenoma (2 papers, 2017 to 2019). An adenoma that arises from the colon or rectum. "Our results showed that APC, CTNNB1, IGF1, and KLF5 were frequently mutated in normal-colorectal adenoma." (PMID 31336886, 2019).
cyst (2 papers, 2020 to 2021). A sac-like closed membranous structure that may be empty or contain fluid or amorphous material. "Increased KLF5 and E2F2 expression levels were observed in tumor tissues, especially in the palisading epithelium and the cyst wall." (PMID 35155179, 2021).
degenerative intervertebral disc disease (2 papers, 2021 to 2023). "The miR-140–3p affects bone marrow stromal cells (BMSCs) in degenerative intervertebral disc disease (IVD) by directly targeting KLF5 and interacting with the N–cadherin/MDM2/Slug axis, thereby regulating regenerative effects in degenerative IVD." (PMID 37325630, 2023).
fibrosis (2 papers, 2022). the formation of excess fibrous connective tissue in an organ or tissue in a reparative or reactive process. "KLF5 may be a key regulator for responding to fibrosis, and further research into its signaling will aid our understanding of cardiac fibrosis and pathogenic tissue fibrosis." (PMID 35457114, 2022). "KLF5 induces TGF-β1 upregulation, contributing to the induction of EMT and tubulointerstitial fibrosis." (PMID 36142408, 2022).
Hyperglycemia (2 papers, 2024 to 2025). An increased concentration of glucose in the blood. "Correction of hyperglycemia with the SGLT2 inhibitor dapagliflozin reverses KLF5 expression in early diabetes." (PMID 38516000, 2024). "On the other hand, hyperglycemia activates iNOS in VSMCs, which, in turn, stimulates KLF5 expression and nitration." (PMID 38516000, 2024).
hypertrophic cardiomyopathy (2 papers, 2024 to 2025). A condition in which the myocardium is hypertrophied without an obvious cause. "To circumvent the hypertrophic cardiomyopathy associated with Klf5 ablation in the systemic modulation experiment in the heart, we adopted an alternative strategy to specifically assess the molecular consequences of Klf5 loss in skeletal muscle." (PMID 40250760, 2025). "Krüppel-like factor 5 (KLF5) is essential in the development of hypertrophic cardiomyopathy." (PMID 39252788, 2024).
lung squamous cell carcinoma (2 papers, 2023 to 2025). "Here, we show that elevated transcription of HERVH proviruses predicted survival of lung squamous cell carcinoma (LUSC) and identified an isoform of CALB1, encoding calbindin, ectopically driven by an upstream HERVH provirus under the control of KLF5, as the mediator of this effect." (PMID 37192000, 2023). "This study delineates a comprehensive landscape of 3447 lung squamous cell carcinoma (LUSC)‐specific oncogenic enhancers (SOEs), unveiling their pivotal role in driving tumor pathogenesis through enrichment of key transcription factors, including SOX2, p63, KLF5, and GRHL2." (PMID 40899632, 2025).
lymph node metastasis (2 papers, 2021). "The upregulation of KLF5 is found to be significantly associated with several aggressive clinico-pathological parameters such as tall cell variant, the presence of extrathyroidal extension, higher stage and lymph node metastasis." (PMID 33430300, 2021).
metastatic prostate carcinoma (2 papers, 2015 to 2019). A carcinoma that arises from the prostate gland and has spread to other anatomic sites. "It has been reported that chromosome 13q21 deletion in human primary and metastatic prostate cancer loci 23 led to the downregulation of KLF5." (PMID 31534497, 2019).
osteoarthritis (2 papers, 2023 to 2025). A noninflammatory degenerative joint disease occurring chiefly in older persons, characterized by degeneration of the articular cartilage, hypertrophy of bone at the margins and changes in the synovial membrane. "For instance, Klf5 acts as a downstream effector of Erg1 in articular cartilage, contributing to chondrocyte hypertrophy and degeneration in osteoarthritis." (PMID 41303527, 2025). "circCDK14 ameliorated IL-1β-induced osteoarthritis chondrocyte injury through the miR-1183/KLF5 pathway." (PMID 36804426, 2023).
periodontitis (2 papers, 2022). An acute or chronic inflammatory process that affects the tissues that surround and support the teeth. "Sirtuin6 (SIRT6) and Krüppel-like factor 5 (KLF5) have been reported to regulate the inflammatory response and play an important role in the development of periodontitis." (PMID 35249460, 2022). "Interestingly, SIRT6 overexpression also promotes osteogenic differentiation and inhibits LPS-induced inflammatory response via suppressing NF-κB pathway in a periodontitis mode constructed by PDLSCs, which could be transcriptionally activated by Krüppel-like factor 5 (KLF5)." (PMID 36060706, 2022). "Therefore, in this study, we aimed to examine the roles of KLF5 and SIRT6 in LPS-induced osteogenic differentiation and inflammatory response of PDLSCs so as to explore the pathogenesis of periodontitis." (PMID 35249460, 2022).
rectal cancer (2 papers, 2021 to 2022). A primary or metastatic malignant neoplasm that affects the rectum. "KLF5 expression was positively related to B cells, CD8+ T cells, and macrophages in rectal cancer." (PMID 35345512, 2022).
Sepsis (2 papers, 2021 to 2024). Sepsis is defined as life-threatening organ dysfunction caused by a dysregulated host response to infection. "Thus, we concluded that ACSS2 promotes pyroptotic cell death of RTECs in the sepsis-induced model of AKI via the KLF5/NF-κB pathway." (PMID 38515158, 2024). "KLF5 was identified as MR on Pediatric Sepsis 1 and 2 networks." (PMID 34680414, 2021). "In terms of the mechanism by which ACSS2 contributed to the induction of RTEC injury by sepsis, we demonstrated that ACSS2 regulates NLRP3-mediated caspase-1 activation and pyroptosis through the KLF5/NF-κB pathway." (PMID 38515158, 2024).
Stroke (2 papers, 2022 to 2024). Sudden impairment of blood flow to a part of the brain due to occlusion or rupture of an artery to the brain. "The Cox regression analysis revealed that individuals carrying the CC genotype of rs11841945 in KLF5 had a higher risk of stroke than those with GG and GC genotypes." (PMID 39187911, 2024). "Collectively, our results demonstrate that butorphanol tartrate displays beneficial capacities on Hcy-induced BBB disruption by upregulating the expressions of KLF5 and Claudin-5, suggesting a novel pharmacological function of butorphanol tartrate on brain cardiovascular diseases such as stroke." (PMID 35245993, 2022).
systemic sclerosis (2 papers, 2019 to 2021). A chronic disorder, possibly autoimmune, marked by excessive production of collagen which results in hardening and thickening of body tissues. "Additionally, in mice with the simultaneous knockdown of Klf5+/− and Fli1+/−, a model of systemic sclerosis, demonstrated severe dermal fibrosis and pulmonary fibrosis." (PMID 33523554, 2021). "Similarly, in dermal fibroblasts of systemic sclerosis, CpG methylation of KLF5 promoter contributed to down‐regulation of KLF5 protein." (PMID 33523554, 2021).
thyroid cancer (2 papers, 2022). "Our results were consistent with those of a previous study showing that KLF5 regulates E-cadherin expression by binding directly to the slug promoter in immortalized mammary epithelial cells and enhances vimentin expression via activation of the nuclear factor-kB pathway in thyroid cancer cells." (PMID 36142408, 2022).
Ureteral obstruction (2 papers, 2019 to 2022). Obstruction of the flow of urine through the ureter. "Although KLF5 has been demonstrated to regulate tubular interstitial fibrosis in models of unilateral ureteral obstruction and subtotal nephrectomy (5/6 nephrectomy), its role in tubular EMT in DN models is yet to be studied." (PMID 36142408, 2022). "Also, KLF5 was shown to play a role in renal inflammation and fibrosis since unilateral ureteral obstruction in mice haploinsufficient for Klf5 resulted in reduced renal injury, fibrosis and infiltrating cells." (PMID 31773180, 2019).
aneurysm (1 paper, 2026). Bulging or ballooning in an area of an artery secondary to arterial wall weakening. "Golph3l upregulation by Klf5 facilitates TNF‐α and TNFSF12 secretion from AngII‐stimulated VSMCs by inducing Golgi compaction, which is essential for AIP and aneurysm development." (PMID 41317401, 2026).
Arrhythmia (1 paper, 2025). Any cardiac rhythm other than the normal sinus rhythm. "We investigated the effect of KLF5-BMSCs transplantation on post-MI arrhythmias." (PMID 40822849, 2025).
autoimmune disease (1 paper, 2019). A disorder resulting from loss of function or tissue destruction of an organ or multiple organs, arising from humoral or cellular immune responses of the individual to their own tissue constituents. "Few studies have reported on the relationship between KLF5 and autoimmune diseases." (PMID 31178864, 2019).
bone metastasis (1 paper, 2021). Transfer of a neoplasm from its primary site to bones. "Establishment of the role of the TGF-β/Ac-KLF5 axis in bone metastatic lesions in this study provides a unique opportunity to better understand the mechanisms underlying bone metastasis." (PMID 33731701, 2021).
calcification (1 paper, 2014). Process by which organic tissue becomes hardened by the physiologic deposit of calcium salts. "Targeting Klf5 or Klf5-regulating signals in VSMCs might represent a novel strategy for prevention and therapy of vascular calcification." (PMID 25205373, 2014).
carotid atherosclerosis (1 paper, 2018). A thickening and loss of elasticity of the walls of carotid arteries that occur with formation of atherosclerotic plaques. "Additionally, MYH11, KLF5, and SPP1 expression patterns were found to be associated with symptomatology of human carotid atherosclerosis." (PMID 29562638, 2018).
cerebral aneurysms (1 paper, 2024). "Very limited literature has indicated its role in the development of cerebral aneurysms and cerebral ischemic injury through the interaction with its direct target Kruppel-like transcription factor 5 (Klf5) or nuclear factor erythroid 2-related factor 2 (Nrf2)." (PMID 39451223, 2024).